ETHE1 (ETHE1 persulfide dioxygenase)
Diseases named in the same sentence as ETHE1 in open-access papers (continued):
Sharing a sentence is not in itself a finding about the gene and the disease.
tumor (8 papers, 2009 to 2025). "As mounting evidence has implicated that VEGF-A plays a vital role in tumor angiogenesis, we subsequently explored the connection between ETHE1 and VEGF-A." (PMID 39198402, 2024). "Our data demonstrated that the downregulation of ETHE1 played an important role in tumor growth and tumor angiogenesis in vitro and in vivo." (PMID 39198402, 2024). "The newly established roles of ETHE1 in tumor angiogenesis provide a rationale for ETHE1 as a novel prognostic indicator for CRC patients and a potential target for further therapeutic investigation." (PMID 39198402, 2024). "Collectively, our study identifies ETHE1 as a novel regulator of tumor angiogenesis, implying its potential as a prognostic biomarker and promising antiangiogenic target for CRC patients." (PMID 39198402, 2024). "While Ozluk E’s study utilized unpaired clinical samples, with a considerably smaller number of normal samples in comparison to tumor samples, our research employed paired samples, enabling a more accurate assessment of ETHE1 expression in CRC." (PMID 39198402, 2024). "To further explore the effects of ETHE1 on tumor angiogenesis in vitro, we collected the conditional medium (CM) from the indicated CRC cells to stimulate HUVECs." (PMID 39198402, 2024). "The results showed that overexpressing ETHE1 dramatically restrains tumor growth compared with control group, resulting smaller tumor size." (PMID 39198402, 2024). "Considering the established role of the Akt signaling pathway and the HIF-1α signaling pathway in tumor angiogenesis, we detected the impact of ETHE1 on these two signaling pathways." (PMID 39198402, 2024). "In summary, these results indicate that ETHE1 plays a critical role in the suppression of tumor growth and tumor angiogenesis of CRC in vivo." (PMID 39198402, 2024). "Subsequently, we explored the function of ETHE1 on tumor angiogenesis using subcutaneous xenograft models in vivo." (PMID 39198402, 2024). "OGDH subunit E2, namely dihydrolipoyllysine-residue succinyltransferase (DLST), cytochrome c oxidase subunit 5B (Complex IV), and persulfide dioxygenase ETHE1 were less-abundant proteins in D tumor samples." (PMID 39195201, 2024). "Be in congruence with in vitro results, IHC analysis of tumor specimens revealed that the expression of VEGF-A was remarkably reduced in ETHE1-overexpressing tumors." (PMID 39198402, 2024). "Significantly, ETHE1 null (KO) CRC cells showed much reduced tumor cell growth and increased median survival time in vivo compared to WT or ETHE1 overexpressing CRC cells." (PMID 31258845, 2019). "Since the established role of STAT3 pathway in the tumor angiogenesis, we first detected whether ETHE1 could influence the activation of STAT3." (PMID 39198402, 2024). "In conclusion, our study initially demonstrates the crucial involvement of ETHE1 in tumor angiogenesis and uncovers a previously unrecognized mechanism whereby ETHE1 facilitates TC45-mediated dephosphorylation of STAT3, thereby suppressing the oncogenic effects of STAT3 signaling in CRC." (PMID 39198402, 2024). "Notably, inhibition of eIF2α phosphorylation through ISRIB or ATF4 knockdown partially abolished the tumor-promoting effect of ETHE1 overexpression." (PMID 37834012, 2023). "Moreover, pharmacological inhibition of eIF2α phosphorylation using integrated stress response inhibitor (ISRIB) or depletion of ATF4 partially abolished the tumor-promoting effects of ETHE1 on TNBC metastasis both in vitro and in mice." (PMID 37834012, 2023). "Taken together, these results suggest that decreased expression of ETHE1 in CRC cells promotes VEGF-A expression and tumor angiogenesis in vitro." (PMID 39198402, 2024). "Here, we reveal that ethylmalonic encephalopathy protein 1 (ETHE1), an essential enzyme in hydrogen sulfide catabolism, inhibits VEGF-A expression and tumor angiogenesis in vitro and in vivo." (PMID 39198402, 2024).
tumor (continued). "Next, we detected ETHE1 protein level in 12 pairs of CRC samples and found that 91.7% (11/12) of tumor tissues had lower ETHE1 expression than the adjacent normal tissues." (PMID 39198402, 2024). "As a result, helping expression induction or activation of ETHE1 and SQOR proteins will increase sulfide scavenging and this would hinder CRC tumor growth." (PMID 34249670, 2021). "High ETHE1 expression increased intestinal and extra-colonic HCT116 and HT29 tumor multiplicity and tumor size (4x fold) compared with scrambled control parental cells." (PMID 31258845, 2019). "The other proteins which showed decreased expression in the tumor tissue included Selenium-binding protein 1, HMG CoA synthase, 1-Cys peroxiredoxin protein 2, Fcgbp protein, Cytochrome c oxidase, subunit Va, and ETHE1 protein." (PMID 19491504, 2009). "Additionally, mice injected (via lateral tail vein) with constitutively expressing ETHE1 HCT116 (1x106) or HT29 (1x106) cells show reduced median survival time, increased tumor incidence, tumor burden, multiplicity and metastasis in vivo." (PMID 31258845, 2019). "In this study, we first demonstrated that ETHE1 plays a key role in TNBC metastasis without affecting TNBC cell and tumor growth." (PMID 37834012, 2023). "ETHE1 had no impact on TNBC cell proliferation and xenograft tumor growth but promoted TNBC cell migration and invasion in vitro and lung metastasis in vivo." (PMID 37834012, 2023).
cancer (3 papers, 2009 to 2023). A tumor composed of atypical neoplastic, often pleomorphic cells that invade other tissues. "However, in our initial studies we did not see activation of this pathway in phenotypically normal intact colon mucosa from FAP patients (cancer initiation), indicating that increased ETHE1 expression involves different mechanisms in different cancer types." (PMID 31258845, 2019).
ETHE1 also shares sentences with these, for which no sentence is quoted: infection (3 papers); mitochondrial disease (3); amyotrophic lateral sclerosis (1); connective tissue disorder (1); energy metabolism disorders (1); Granuloma (1); Huntington disease (1); metabolic disorders (1); mitochondrial neurogastrointestinal encephalomyopathy (1); optic atrophy (1); Parkinson disease (1); polycystic ovary syndrome (1); schizophrenia (1); Spastic paraplegia (1); triple-negative breast carcinoma (1).